RNU6-410P (RNA, U6 small nuclear 410, pseudogene)
Gene: Small nuclear RNA gene on chromosome 4 (55,031,965 to 55,032,071, reverse strand). Ensembl gene ENSG00000252815.
Homologues: Orthologues: chimpanzee U6 (100% identical), mouse Gm24697 (69% identical), dog U6 (67% identical), guinea pig U6 (66% identical), rabbit U6 (58% identical), rabbit U6 (57% identical). Paralogues in human: RNU6-1152P (78% identical), RNU6-73P (78% identical), RNU6-1011P (77% identical), RNU6-31P (77% identical), RNU6-552P (77% identical), RNU6-820P (77% identical), RNU6-12P (76% identical), RNU6-13P (76% identical), RNU6-15P (76% identical), RNU6-166P (76% identical), RNU6-211P (76% identical), RNU6-32P (76% identical), and 1284 more.